MIR6859-3 (microRNA 6859-3)
Synonyms: hsa-mir-6859-3
Gene: MicroRNA gene on chromosome 15 (101,973,524 to 101,973,591, forward strand). Ensembl gene ENSG00000275449.
Homologues: Paralogues in human: MIR6859-1 (100% identical), MIR6859-2 (100% identical), MIR6859-4 (100% identical).